TLR2 (toll like receptor 2)
Diseases named in the same sentence as TLR2 in open-access papers (continued):
Sharing a sentence is not in itself a finding about the gene and the disease.
cerebral malaria (9 papers, 2012 to 2025). A sequestration of Plasmodium falciparum in the brain, which can cause coma and/or seizures. "For example, a Toll-like receptor 2 (TLR2) Δ22 polymorphism was associated with protection from cerebral malaria in a case-control study." (PMID 39847577, 2025). "TLR2 is associated with protection from cerebral malaria and therapeutic targeting of TLRs has been shown to prevent experimental cerebral malaria." (PMID 23843682, 2013). "In the current study, the role of TLR2 insertion/deletion polymorphisms, Δ22 and GTn, in the pathogenesis of cerebral malaria was evaluated." (PMID 22336003, 2012). "Reduced inducible TLR2 expression may lead to attenuated pro-inflammatory responses, a potential mechanism of protection from cerebral malaria present in individuals heterozygous for the TLR2 Δ22 polymorphism." (PMID 22336003, 2012). "Collectively, this data suggest that heterozygosity for a 22 bp deletion within the first un-translated exon of TLR2 is associated with protection from cerebral malaria, and that this protection may be due to a dampening of the pro-inflammatory response." (PMID 22336003, 2012). "Although the role of TLR2 and TLR4 in malaria remain obscure, TLR9 deficient mice were reported to be resistant to PbA-induced cerebral malaria, indicating a role in pathology of TLR9 rather than cerebral malaria protection." (PMID 32944216, 2020). "Serum TNF, IFN-γ, IL-1β, IL-6, and IL-10 did not vary based on either TLR2 Δ22 or GTn genotype in children with cerebral malaria." (PMID 22336003, 2012). "Although the role of TLR2 and TLR4 in malaria remain unclear, mice deficient in TLR9 were reported to be resistant to PbA-induced experimental cerebral malaria (ECM), suggesting a pathological role of TLR9 rather than a protective role during cerebral malaria." (PMID 29495555, 2018). "Notably, Plasmodium GPI were described to be primarily recognized by TLR2 or heterodimers of TLR2/1 and TLR2/6, yet TLR-deficiency did not protect mice from experimental cerebral malaria (ECM), indicating that TLR-mediated pro-inflammatory immune responses are not critical in the development of ECM." (PMID 28560184, 2017). "However, observations that TLR2/4 double knockout mice show no resistance to cerebral malaria prompted the question whether additional receptors might be involved in this process." (PMID 28560184, 2017). "However, TLR2 and 9 but not TLR4, 5, and 7 were involved in cerebral malaria (CM) infection using Plasmodium berghei ANKA (PbA)." (PMID 27511368, 2016).
Cirrhosis (9 papers, 2016 to 2025). A chronic disorder of the liver in which liver tissue becomes scarred and is partially replaced by regenerative nodules and fibrotic tissue resulting in loss of liver function. "TLR2 is upregulated only after incubation with plasma from patients with alcohol-associated cirrhosis, while TLR4 is upregulated in neutrophils treated with plasma from patients with both alcohol-associated and viral cirrhosis." (PMID 37822786, 2023). "We noted significantly lower levels of TLR2, 4 in cirrhosis most likely associated with cirrhosis associated immune dysfunction." (PMID 27992443, 2016). "Similarly, expression of the Toll-like receptor 2 (TLR2) was higher in all CD8+ T cells in BA-associated cirrhosis compared to the control group." (PMID 40607400, 2025). "Consecutive patients with cirrhosis and ascitic fluid were distributed by TLR2 rs4696480, TLR4 rs4986790, and TLR9 rs187084 single-nucleotide polymorphisms." (PMID 28418003, 2017). "We evaluated the incidence of 3 well-known polymorphisms in TLR-2, TLR-4 and TLR-9 in patients with cirrhosis." (PMID 28418003, 2017). "The aim of the present study was to evaluate the incidence of relevant polymorphisms in TLR-2, TLR-4 and TLR-9, specific receptors of bacterial products which are frequently translocated from the gut in patients with cirrhosis." (PMID 28418003, 2017). "In summary, polymorphisms in TLR-2, TLR-4 and TLR-9 genes are associated with an increased bacterial antigen burden and a deficient pro-inflammatory cytokine response in patients with cirrhosis." (PMID 28418003, 2017). "The IL28B CC genotype exerts a protective effect on CHC and the development of cirrhosis and HCC, while the TLR-2 del/del genotype was associated with an increased risk of HCC." (PMID 27917361, 2016). "We have evaluated the effect of TLR2 rs4696480, TLR4 rs4986790 and TLR9 rs187084 polymorphisms in the bacterial antigen load and the pro-inflammatory mediator levels in the blood of a consecutive series of patients with cirrhosis and AF." (PMID 28418003, 2017). "Endotoxin receptors TLR2 and TLR4 are upregulated in healthy donor neutrophils after incubation with cirrhotic plasma and in neutrophils from patients with cirrhosis." (PMID 37822786, 2023).
cognitive decline (9 papers, 2011 to 2026). "We distinguished a role of TLR-4 in the AβOs and TLR-2 in the toxic effect of α-SynOs by measuring cognitive decline found similar results when glial activation was considered." (PMID 36982988, 2023). "ICV α-SynOs induced cognitive decline with glial activation, both effects being antagonized by TLR-2 antagonist." (PMID 36982988, 2023). "We have previously demonstrated that TLR2 is important to delay the cognitive decline in a mouse model of AD." (PMID 21235801, 2011). "However, 1 study has shown that genetic knockdown of TLR2 accelerates the cognitive decline in APP-Tg mice." (PMID 29990310, 2018).
endometriosis (9 papers, 2017 to 2025). The growth of functional endometrial tissue in anatomic sites outside the uterine body. "We developed a new infection-induced mouse model of endometriosis with wild type and Tlr2-deficient mice." (PMID 31636643, 2019). "Individuals with endometriosis have significantly higher TLR2 and TLR9 concentrations in peritoneal fluid than healthy controls." (PMID 40508002, 2025). "Hypothetically, TLR2-mediated expression of DCs in patients with endometriosis is the trigger of the endogenous pattern of activation of TLRs by DAMPs." (PMID 32751735, 2020). "TLR2 expression seems to play an important role in endometriosis, potentially in the context of DAMP-mediated pathway." (PMID 32751735, 2020). "Our study showed the importance of TLR2 expression, mainly on myeloid dendritic cells (mDCs) and B cells in patients with endometriosis." (PMID 32751735, 2020). "Our study shows that TLR2 expression on the observed immune cells plays a role in endometriosis, not only for the dynamics of these cells’ presence in the course of endometriosis, but also in impacting disease manifestation." (PMID 32751735, 2020). "Our study shows that myeloid DCs expressing TLR2 appear to be important in the pathophysiology of endometriosis, in view of their increased levels compared with the control group." (PMID 32751735, 2020). "In summary, we observed that U. urealyticum infection increases inflammatory mediators, adhesion molecules, and MMP-2 expression in PMCs through TLR2 signaling and promotes endometriosis." (PMID 31636643, 2019). "Increased TLR2 B cells and myeloid dendritic cells correlate with severe endometriosis." (PMID 40508002, 2025). "Beyond TLR4, TLR2 also appears to play a significant role in the pathogenesis of endometriosis." (PMID 40862752, 2025). "Researchers assessed the levels of numerous immunological cell subsets (dendritic cells, monocytes, and basic peripheral blood lymphocytes) expressing TLR2 and evaluated the potential correlation between the expression of TLR2 and the clinical characteristics of endometriosis patients." (PMID 37033937, 2023). "In the same year, another study reported that the expression of TLR4 and TLR2 were higher in the endometrial tissues from endometriosis patients than that of normal endometrium, suggesting the potential role of TLR2 and TLR4 in the development of endometriosis." (PMID 37033937, 2023). "Diagnostic accuracy was excellent for B lymphocyte CD19+TLR-2+ parameters, which showed negative correlation with infertility, adhesion, and 3–4 stages in endometriosis patients." (PMID 32751735, 2020). "Interestingly, the level of T CD8+TLR2+ is markedly higher in the stages 3–4 of endometriosis than in stages 1–2, suggesting the potential mobilization of these cells in more advanced stages of the disease." (PMID 32751735, 2020). "Similarly, as in several inflammatory conditions, possibly in endometriosis, TLR2 reacts on an endogenous ligand to trigger DCs." (PMID 32751735, 2020). "The aim of the studies was to evaluate the levels of several subsets of immunological cells (dendritic cells, monocytes, and basic peripheral blood lymphocytes) expressing TLR2, in order to determine a possible correlation between the expression of TLR2 and the clinical outcomes of endometriosis." (PMID 32751735, 2020). "Based on this previous knowledge, we hypothesized that U. urealyticum infection might contribute to the development of endometriosis by inducing the production of inflammatory mediators by PMCs, possibly through TLR2." (PMID 31636643, 2019). "We hypothesized that Ureaplasma urealyticum infection might contribute to the development of endometriosis by inducing the production of inflammatory mediators by peritoneal mesothelial cells (PMCs), possibly through TLR2." (PMID 31636643, 2019). "TLR2 may play a crucial role in the pathogenesis of endometriosis patients." (PMID 37033937, 2023).
endometriosis (continued). "In a mouse model, Ureoplasma urealyticum infection promotes endometriosis by enhancing inflammatory mediators and MMP-2 expression via TLR2 signaling." (PMID 40508002, 2025). "We observed markedly higher expression of TLR2, TLR3, TLR4, TLR7, TLR8, and TLR9 on CD4+, CD8+, and CD19+ lymphocytes in the endometriosis group, indicating their active participation in modulating immune responses in the disease setting." (PMID 40862752, 2025). "Collectively, U. urealyticum infection promotes the development of endometriosis by increasing inflammatory mediators, adhesion molecules, and MMP-2 expression in PMCs through TLR2 signaling." (PMID 31636643, 2019). "Decrease of non-classical monocyte CD14+CD16+TLR2+ values below their prognostic value has good discriminative power between endometriosis patients with and without adhesion." (PMID 32751735, 2020). "Our study also showed a negative association of B lymphocyte CD19+TLR-2+ levels with infertility, adhesion, and stages III and IV in patients with endometriosis." (PMID 32751735, 2020). "In our study, the levels of nonclassical monocytes CD14+CD16+TLR2+ in patients with endometriosis seem to have good discrimination power between endometriosis patients with and without adhesions." (PMID 32751735, 2020). "Our findings suggest that the levels of TLR2-expressing cells, particularly mDCs and B lymphocytes, may be an effective biomarker of endometriosis, because the disease currently lacks clinically useful noninvasive biomarkers enabling early and cost-effective diagnosis." (PMID 32751735, 2020).
gram-negative bacterial infections (9 papers, 2011 to 2025). Infections caused by bacteria that show up as pink (negative) when treated by the gram-staining method. "The development of innate immune responses against Gram-positive and Gram-negative bacterial infections is launched by the activation of TLR2 and TLR4, respectively." (PMID 32466097, 2020). "Identification of both Lyn and TLR2 as novel regulatory factors in autophagy may implicate their therapeutic potential for control of Gram-negative bacterial infection." (PMID 26735693, 2016). "TLR2-deficient macrophages have been shown to be hyporesponsive to Staphylococcus aureus peptidoglycan, and C3H/Hej mice with missense mutations of the TLR4 gene were highly susceptible to Gram-negative bacterial infection." (PMID 25967535, 2015). "Studies in other fish species like mrigal (Cirrhinus mrigala) and rohu (labeo rohita) showed that TLR2 expression was induced following exposure to PGN and LTA, as well as Gram-positive or Gram-negative bacterial infection." (PMID 37897005, 2023). "TLR2 and TLR4 are components of the innate immune response and play a crucial role in host defense against Gram-positive and Gram-negative bacterial infection." (PMID 26147469, 2015). "A remarkable feature of TLR2 and TLR4 is their ability to cooperate with CD14 on the host cell surface in sensing LPS of Gram negative bacterial infection." (PMID 23492674, 2011). "We show Gram-negative bacterial infection upregulates Siglec-E expression via the TLR4/MyD88/JNK/NF-κB/AP-1 signaling pathway, whereas infection with Gram-positive bacteria downregulates Siglec-E expression via the TLR2/RANKL/TRAF6/Syk signaling pathway." (PMID 32889432, 2020). "However, although Gram-negative bacterial infection is primarily regulated by TLR-4, TLR-2 activation is thought to play an import modulating role." (PMID 25025775, 2014).
lung disease (9 papers, 2005 to 2024). "TLR: Three extracts, #4, #8 and #14 downregulated the levels of Toll-like receptor 2 (TLR2), which has been implicated in numerous inflammatory diseases, including pulmonary diseases and ARDS." (PMID 33465050, 2021). "While gut microbial translocation is often cited as an etiology for TLR2 activation in HIV-infected patients, underlying lung disease such as COPD is also associated with TLR2 activation, possibly due to airway colonization with non-typeable Haemophilus influenzae." (PMID 23457535, 2013).
myocarditis (9 papers, 2012 to 2025). Myocarditis is a condition that is characterized by inflammation of the heart muscle (myocardium). "While previous reports demonstrated a pathogenic role for TLR4 this is the first report that TLR2 is preferentially up-regulated in CVB3 infected female mice or that signaling through this TLR directly causes myocarditis resistance." (PMID 23241283, 2012). "Mice were additionally treated with PAM3CSK4 (TLR2 agonist) or ultrapure LPS (TLR4 agonist) on the same day as CVB3 infection or 3 days post infection to confirm their role in myocarditis susceptibility." (PMID 23241283, 2012). "Cardiac myosin–derived TLR2 ligands exacerbated Th17-related cytokine production by myocarditis monocytes, which was inhibited by an anti-TLR2 antibody." (PMID 39817455, 2025). "At the chronic stages of myocarditis (28 days pi CVB3) only Tlr2, Tlr4 and Tlr6 showed still an increased gene expression." (PMID 29538462, 2018). "During acute CVB3-induced myocarditis most of the plasma membrane and intracellular localized TLRs showed an enhanced gene expression, however, Tlr2, Tlr3, Tlr6, Tlr7, and Tlr9 displayed by far the highest increase of mRNA expression during acute disease." (PMID 29538462, 2018). "In acute CVB3 myocarditis (7 days post infection (pi)) all plasma membrane localized TLRs showed an increased gene expression, however, the highest increase in gene expression levels displayed Tlr2 and Tlr6." (PMID 29538462, 2018). "Further evidence for the role of TLR2 and TLR4 in CVB3 myocarditis was obtained by treating male and female C57Bl/6 mice with either 50μg PAM3CSK4 (PAM; TLR2 agonist) or 20 mg/kg Ultra-Pure LPS (UP-LPS; TLR4 agonist)." (PMID 23241283, 2012). "While microarray analysis showed sex differences in TLR2 expression, a role for TLR4 in CVB3 myocarditis has also been shown." (PMID 23241283, 2012). "However, in patients with myocarditis, TLR1, TLR2, and TLR7 are overexpressed at the mRNA level." (PMID 38715608, 2024). "Nor has the role of TLR2 in CVB3 myocarditis been adequately investigated." (PMID 23241283, 2012).
pneumococcal pneumonia (9 papers, 2008 to 2023). A febrile disease caused by STREPTOCOCCUS PNEUMONIAE. "Our laboratory recently demonstrated that TLR2 and TLR4 interact in the recognition of S. pneumoniae and that pneumolysin-induced TLR4 signalling can compensate for TLR2 deficiency during pneumococcal pneumonia." (PMID 22721450, 2012). "TLR2 is also an important mediator of the damage associated with pneumococcal pneumonia." (PMID 27981251, 2016). "We here addressed the question whether an intact spleen, which plays an important role in the primary defense against pneumococci, can compensate for TLR2 deficiency during pneumococcal pneumonia, thereby explaining the insignificant role of TLR2 in the otherwise immune competent host." (PMID 22721450, 2012). "We wanted to investigate if in absence of an intact spleen as a first line of defense, the role of TLR2 during pneumococcal pneumonia becomes more significant, thereby explaining its insignificant role during infections in immune competent hosts." (PMID 22721450, 2012). "In otherwise immune competent mice, TLR2 deficiency does not influence mortality or bacterial growth during pneumococcal pneumonia." (PMID 22721450, 2012). "We here postulated that the potentially protective properties of TLR2 in host defense during pneumococcal pneumonia might become visible if another important line of defense (i.e. an intact spleen) would be eliminated." (PMID 22721450, 2012). "Among these, TLR2 and TLR4 are thought to be critical in bacterial infections and have been studied in pneumococcal pneumonia." (PMID 29922273, 2018). "Although Toll-like receptor (TLR)-2 is considered the major receptor for Gram-positive bacteria in innate immunity, it does not play a major role in host defense against pneumococcal pneumonia." (PMID 22721450, 2012). "Previous studies have established that TLR2 does not contribute to an effective antibacterial defense during pneumococcal pneumonia, suggesting that other components of the immune system are sufficient to maintain an adequate response against S. pneumoniae." (PMID 22721450, 2012). "The present data clearly show that even in the hyper-vulnerable asplenic host TLR2 does not contribute to defense against pneumococcal pneumonia, as reflected by similar mortality and bacterial growth in TLR2KO and WT mice." (PMID 22721450, 2012). "Nonetheless, our laboratory and others have demonstrated that TLR2 does not play a major role in host defense against pneumococcal pneumonia." (PMID 22721450, 2012). "Although the pneumococcus expresses several potent TLR2 ligands, our laboratory previously could not demonstrate a decisive role for TLR2 in host defence against pneumococcal pneumonia." (PMID 17711480, 2008). "Considering that especially low TNF-α concentrations in the lungs early after induction of pneumococcal pneumonia are important for limiting the growth of S. pneumoniae, this differential response may have contributed to the enhanced growth of S. pneumoniae PLN in TLR2 KO mice." (PMID 17711480, 2008).